FLNB (filamin B)
Diseases named in the same sentence as FLNB in open-access papers (continued):
Sharing a sentence is not in itself a finding about the gene and the disease.
ovarian carcinoma (4 papers, 2017 to 2025). A malignant neoplasm originating from the surface ovarian epithelium. "Loss of FLNB inhibits vascular permeability and, in ovarian cancer cells, promotes MMP9-mediated tumour invasion and VEGFA-mediated angiogenesis plus induces tumour growth." (PMID 41373535, 2025). "The filamin B (FLNB) gene was proved to be downregulated by linc-ROR by acting as a sponge for miR-145 in ovarian cancer." (PMID 36827545, 2023). "It has been shown that filamin B can suppress the growth and metastasis of human ovarian cancer by down-regulating the activity of MMP-9 and secretion of VEGF-A." (PMID 28538838, 2017). "In ovarian cancer, the gene set enrichment analysis (GSEA) of FLNB and SOX9 genes revealed distinct and overlapping pathway involvements." (PMID 38529261, 2024). "Filamin B (FLNB) suppresses the growth and metastasis of human ovarian cancer by down-regulating the activity of MMP-9 and secretion of vascular endothelial growth factor-A (VEGF-A)." (PMID 28538838, 2017). "By analyzing the correlation between DYRK3 and EMT-related genes in TCGA-ovarian cancer dataset, we observed a positive correlation between DYRK3 with FLNB and SOX9, both of which had been well acknowledged as oncogenic molecules in tumorigenesis and cancer progression." (PMID 38529261, 2024).
pancreatic cancer (3 papers, 2021 to 2022). "Furthermore, filamin B is positively regulated by the pancreatic cancer-associated transcription factor MYB, which is suggested to be a potential biomarker of PDAC aggression." (PMID 35174086, 2022). "Additionally, the actin cross-linker and mechanoresponsive protein, filamin B, has increased expression in pancreatic cancer primary tumors and has been correlated with reduced patient survival through the analysis of publicly available data on the Oncomine and UALCAN databases." (PMID 35174086, 2022).
preeclampsia (3 papers, 2013 to 2025). Preeclampsia is a hypertensive disorder of pregnancy that is characterized by new-onset hypertension with proteinuria presenting after 20 weeks of gestation, and depending on mild or severe forms may initially present with severe headache, visual disturbances, and hyperreflexia. "However, emerging evidence indicates that FLNB may contribute to the dysregulation of cellular pathways implicated in preeclampsia." (PMID 38099221, 2023). "The multifunctional nature of FLNB suggests potential interactions with established preeclampsia factors, including angiogenic/antiangiogenic proteins, insulin signaling defects, and immune dysregulation." (PMID 38099221, 2023). "While the precise molecular mechanisms in PE are unknown, FLNB participates in preeclampsia-related pathways, including transcriptional regulation, alternative splicing, and apoptosis regulation in trophoblastic cells." (PMID 38099221, 2023). "Downregulation of FLNB also contributes to decreased expression of ERK, MMP-2, and MMP-9, which in turn reduces placental trophoblast invasion in preeclampsia." (PMID 40638605, 2025). "FLT1, LEP, INHA and ENG genes were identified according to the literature, however, we also found other genes as FLNB, INHBA, NDRG1 and LYN highly significant but underexplored during normal pregnancy or preeclampsia." (PMID 24219996, 2013).
scoliosis (3 papers, 2016 to 2025). A congenital or acquired spinal deformity characterized by lateral curvature of the spine. "Among the identified variants, FLNB and LMNA, both associated with autosomal dominant disorders that include scoliosis in their phenotypic spectrum, emerge as particularly significant contributors to severe IS, with FLNB showing statistical enrichment compared to controls (p < 0.05)." (PMID 41210864, 2025).
deafness (2 papers, 2023). An inherited or acquired condition characterized by the complete loss of the ability to hear from one or both ears. "Although inherited mutations in MYO1C have been described for deafness in humans and mice, MYO1C’s role in cytoskeletal development, similar to that of FLNB, suggests a potential mechanism for inherited lethal SNVs in stillbirth." (PMID 36800380, 2023).
dwarfism (2 papers, 2014 to 2025). "In general, loss of FlnB function in mice leads to two major skeletal phenotypes, dwarfism, and premature mineralization with bone fusion." (PMID 24551245, 2014). "These microstructural characteristics are likely the result of altered skeletal development and growth, as FLNB knock-out mice exhibit delayed bone formation in the long bones, along with dwarfism and early fusion of the vertebral, carpal, and tarsal bones." (PMID 41062856, 2025).
allergies (1 paper, 2020). "Furthermore, another study revealed that the downstream regulation of FLNB suppresses ERK1/2 signaling, suggesting another functional mechanism for FLNB downregulation in DCs from individuals with allergies." (PMID 33207814, 2020).
Aortic dissection (1 paper, 2014). Aortic dissection refers to a tear in the intimal layer of the aorta causing a separation between the intima and the medial layers of the aorta. "Mutations and perturbation in the FLNA and FLNB genes are known to cause different developmental disorders in humans, such as bone anomalies, periventricular heterotopia, aortic dissection and aneurysm." (PMID 25419056, 2014).
atelosteogenesis type I (1 paper, 2018). A perinatally lethal skeletal dysplasia characterized by severe short-limbed dwarfism, joint dislocations, club feet along with distinctive facies and radiographic findings. "Atelosteogenesis type I (AOI) is an autosomal dominant skeletal dysplasia caused by mutations in the filaminB (FLNB) gene with classic and well-recognizable clinical findings." (PMID 30231296, 2018).
breast tumors (1 paper, 2022). "Higher FLNA expression was detected in TNBC respect to luminal BC subgroup, whereas FLNB as well as FLNC expression levels were found higher in luminal breast tumors respect to TNBC." (PMID 35655319, 2022).
C. perfringens infection (1 paper, 2021). "In our study, at Day 5 post C. perfringens infection, FLNB and SPEG were significantly upregulated, suggesting the association with increased cytoskeletal network activities and myocyte repairing/development." (PMID 34959561, 2021). "Forty-eight genes in the host were upregulated with significant differences following C. perfringens infection, including top enriched CCTα, Chromobox 3, and Filamin B. Inflammation and lipid signaling are intermingled modulators of homeostasis and immunity." (PMID 34959561, 2021).
cleft palate (1 paper, 2023). Cleft palate is a fissure type embryopathy that affects the soft and hard palate to varying degrees. "Pathogenic variants in FLNB cause disorders presenting a spectrum of phenotypes, which sometimes includes cleft palate." (PMID 36830605, 2023).
clubfoot (1 paper, 2024). The most common congenital deformation of the foot, occurring in 1 of 1,000 live births. "Initially, genes associatedwith clubfoot (PITX1, TBX4, HOXA9, HOXD10, HOXD12,HOXD13, HOXA9, TPM1, TPM2, COL9A1, FLNB, CASP8,CASP10, UTX, CHD1, RIPPLY2, CAND2, WNT7) werescreened for potential variants." (PMID 38952703, 2024).
disc degeneration (1 paper, 2022). "This work delineates the mechanism by which FLNB modulates canonical and noncanonical TGFβ/BMP signaling through i-Smads and provides a targeted molecular model to understand progressive disc degeneration." (PMID 35474298, 2022).
embryonic cancers (1 paper, 2020). "We tested the expression of FLNA, FLNB and FLNC in different germ cell cancer tissues using an Affymetrix expression array analysis and found abundant expression of FLNA, in particular in seminonas, embryonic cancers and teratomas." (PMID 33266100, 2020).
focal segmental glomerulosclerosis (1 paper, 2022). A renal disorder characterized by sclerotic lesions in the glomeruli. "Previous studies showed Filamin B levels to be elevated in patients suffering from focal segmental glomerulosclerosis (FSGS) and in injured murine podocytes, but its functional role and whether the increased expression levels are protective or pathogenic, remain elusive." (PMID 35922155, 2022).
glioblastoma (1 paper, 2023). The most malignant astrocytic tumor (WHO grade IV). "Lower expression of both FLNB and CDH18 have been shown to have anti-invasive effects in mouse embryonic fibroblasts and glioblastoma cells." (PMID 38033034, 2023).
glioma (1 paper, 2009). A benign or malignant brain and spinal cord tumor that arises from glial cells (astrocytes, oligodendrocytes, ependymal cells).
hereditary cancer (1 paper, 2023). Malignant neoplasms occurring in families at a rate greater than that expected by chance and caused by germline mutations in a specific gene. "No clinically significant variants were identified in genes associated with hereditary cancer or in the FLNB gene." (PMID 37433679, 2023).
hypertrophic cardiomyopathy (1 paper, 2019). A condition in which the myocardium is hypertrophied without an obvious cause. "However, the deregulation of miRNAs and FLNB editing might contribute to hypertrophic cardiomyopathy." (PMID 31039163, 2019).
lung adenocarcinoma (1 paper, 2024). A carcinoma that arises from the lung and is characterized by the presence of malignant glandular epithelial cells. "In this study, we found that FLNB was an independent prognostic risk factor for OC, aligned with previous research in lung adenocarcinoma." (PMID 38694875, 2024).
malignant melanoma (1 paper, 2025). "TRIP4, which is associated with malignant melanoma, was repressed by PTCH1 but to a lesser extent than PTCH1/FLNB double knockdown, perhaps reflecting the more aggressive nature of mBCC." (PMID 41373535, 2025).
mesothelioma (1 paper, 2022). A usually malignant and aggressive neoplasm of the mesothelium which is often associated with exposure to asbestos. "We thereby confirmed, in mesothelioma tumor samples, the inverse relationship between RNA editing at splice sites and the alternative splicing of Filamin B (FLNB) as observed in RNA‐seq data from GTEx consortium, as well as its association with ADAR2 expression." (PMID 36221913, 2022).
myocarditis (1 paper, 2013). Myocarditis is a condition that is characterized by inflammation of the heart muscle (myocardium). "In contrast to filamin A and filamin B, the high expression of filamin C in myocytes suggests that filamin C represents a sensitive and specific marker of the subclinical myocarditis that accompanies KD." (PMID 23281308, 2013).
orofacial clefting (1 paper, 2010). "In conclusion, with the possible exception of FLNB, HIC1 and ZNF189, our data suggest that maternal genes do not contribute significantly to orofacial clefting in the Norwegian and Danish samples." (PMID 20634891, 2010).
osteoarthritis (1 paper, 2025). A noninflammatory degenerative joint disease occurring chiefly in older persons, characterized by degeneration of the articular cartilage, hypertrophy of bone at the margins and changes in the synovial membrane. "Children with ACAN mutations may develop early-onset joint pain or osteoarthritis, while variants in COL2A1 or FLNB may lead to orthopedic complications." (PMID 40723048, 2025).
osteoporosis (1 paper, 2013). A condition of reduced bone mass, with decreased cortical thickness and a decrease in the number and size of the trabeculae of cancellous bone (but normal chemical composition), resulting in increased fracture incidence. "Although providing more support of a role for the FLNB gene in osteoporosis, comparisons with this study and our previous study must be done with caution due to differences in study design as well as differences in the ethnicity of the study subjects." (PMID 24176111, 2013).
osteosarcoma (1 paper, 2022). A usually aggressive malignant bone-forming mesenchymal neoplasm, predominantly affecting adolescents and young adults. "Nevertheless, Saos-2 (human osteosarcoma cells) and ATDC5 (mouse teratocarcinoma cells) were, respectively, osteoblastic and chondrogenic cell lines, which were much more suitable for the study of FLNB in skeletal diseases." (PMID 35832491, 2022).
psoriasis (1 paper, 2025). An autoimmune condition characterized by red, well-delineated plaques with silvery scales that are usually on the extensor surfaces and scalp. "Venn diagram analysis revealed four overlapping genes, SLC3A2, GYS1, FLNA, and FLNB, which may serve as core candidates linking disulfidptosis to the molecular mechanisms of psoriasis." (PMID 41224720, 2025).
renal clear cell carcinomas (1 paper, 2025). "Previous studies have shown that FLNB knockdown in various cancer cell types—including ovarian, cervical, and renal clear cell carcinomas—enhances their proliferative capacity and invasiveness." (PMID 40638605, 2025).
Stillbirth (1 paper, 2023). Death of the fetus in utero after at least 22 weeks of gestation. "Though the study was limited in ascertaining de novo from inherited variants, due to unavailability of paternal DNA, genes were reported by the authors that are either lethal, known to cause disease, or increase stillbirth risk (e.g., CCR5, FAT1, FLNB, INPP5K, MYO1C, PLOD2)." (PMID 36800380, 2023). "Missense actin mutations in FLNB leading to atelosteogenesis type I and lethal skeletal dysplasia or inhibition of ERK/MMP-2 and MMP-9 pathways that are critical for trophoblast invasion, may be possible mechanisms of potentially lethal de novo FLNB SNVs in stillbirth etiology." (PMID 36800380, 2023).
teratocarcinoma (1 paper, 2022). A germ cell tumor characterized by the presence of an embryonal carcinoma component and a teratoma component. "Besides performing functional study in Saos-2 cells, we also explored the pathogenic role of both FLNB variants in the ATDC5 cell line which was derived from mouse teratocarcinoma cells and characterized as a chondrogenic cell line." (PMID 35832491, 2022).
virus infection (1 paper, 2024). "Thus, C4 associates with FLNB for a different reason, suggesting that the cytoskeleton has further uncharacterized roles during virus infection." (PMID 38412044, 2024).
tumor (30 papers, 2005 to 2025). "PTCH1 alone does not result in a morphoeic phenotype being common to both mBCC and nodBCC; however, loss-of-function (as a potential tumour-suppressor gene) drivers FLNB and HECTD4 were identified as being morphoeic-specific." (PMID 41373535, 2025). "Nevertheless, in contrast to FLNA, FLNB deficiency enhanced RAS-induced tumor growth and metastasis through the RAS/ERK pathway." (PMID 34485398, 2021). "FLNB is a potential tumour suppressor, with its loss producing a morphoeic phenotype in vitro." (PMID 41373535, 2025). "Filamin B (FLNB) is known to suppress local tumor growth, angiogenesis, and metastasis, and its loss may also play a significant role in B-ALL." (PMID 38139431, 2023). "Substitution of methionine by valine at residue 2,269 in filamin B (FLNB) due to recoding by ADAR1 abrogates tumor suppressive activities of the protein, leading to cell-cycle progression and invasion." (PMID 39126156, 2025). "We also observed several genes that have been reported to change the editing level in cancer and even drive early tumor invasion and metastasis, including FLNB, SLC22A3, and AZIN1, which had significantly different editing levels in PDAC." (PMID 36895481, 2023). "FLNB was also shown to be involved in tumor growth and metastases." (PMID 29682400, 2017). "(B–C) Kaplan-Meier plots showing data from TCGA PRAD cohort of percentage of tumours that are free of biochemical recurrence versus time in years, associated with expressing the alternative splice isoforms of (B) RPS24 exon 5 (PSI cut off 0.44), and (C) FLNB exon 30 (PSI cut off 0.78)." (PMID 31478829, 2019). "The expressions in the tumor tissues also generally correlated with MIR31HG levels (r = 0.523, r = 0.367, and r = 0.287 for FLNB, LAMA3, and MMP1, respectively)." (PMID 36980216, 2023). "FLNB exon 31 (activated by ESRP2) actually shows slightly reduced splicing inclusion in larger, more aggressive tumours." (PMID 31478829, 2019). "The phenomenon leads to hyperediting of FLNB (Filamin B) and AZIN1 mRNA, the latter candidate shows a gain-of-function phenotype, leading to aggressive tumor behavior." (PMID 28398248, 2017). "FLNB, SLC7A11, and CD2AP were lowly expressed in almost all major cell types, but significant expression difference was also found in fibroblasts between tumor and normal tissue." (PMID 38694875, 2024). "However, zebrafish and mouse model systems showed that silencing FLNB increased MMP-9 expression in endothelial and cancer cells, which enhanced tumor angiogenesis and VEGF-A secretion, then promoted tumor growth and metastasis." (PMID 38694875, 2024). "However, only a few coding RNA editing sites have been characterized, such as AZIN1, GABRA3, FLNB, SLC22A3, and COPA, which can affect tumor progression." (PMID 36895481, 2023). "With the exception of FLNB and MYL6, the remaining 13 DRGs were significantly differentially expressed in the normal and tumor groups of the pancreas, and most DRGs shows higher expression in tumor groups." (PMID 38097783, 2023). "In this study, we identified POSTN and FLNB as potential mediators of the effects of EVs on GSC and HMVEC behavior confirming that EVs play a crucial role in the intercellular communication by delivering bioactive molecules in the surrounding milieu modulating tumor microenvironment." (PMID 38347567, 2024). "Targeting FLNB to regulate S1PR1 localization may provide additional therapeutic interventions for treating vascular inflammation and related vascular diseases as well as tumor angiogenesis." (PMID 37220855, 2023). "However, 13-cis-RA did not significantly modulate RET, RGS16, FLNB, and EGR1 expression in the tissue samples from tumour-bearing animals treated for 5 days." (PMID 16012519, 2005).